RNU6-326P (RNA, U6 small nuclear 326, pseudogene)
Gene: Small nuclear RNA gene on chromosome 7 (45,843,634 to 45,843,740, forward strand). Ensembl gene ENSG00000202350.
Homologues: Orthologues: chimpanzee U6 (99% identical). Paralogues in human: RNU6-1085P (96% identical), RNU6-1335P (95% identical), RNU6-16P (89% identical), RNU6-25P (89% identical), RNU6-29P (89% identical), RNU6-38P (89% identical), RNU6-1 (88% identical), RNU6-11P (88% identical), RNU6-2 (88% identical), RNU6-20P (88% identical), RNU6-37P (88% identical), RNU6-393P (88% identical), and 1290 more.